EPO (erythropoietin)
Diseases named in the same sentence as EPO in open-access papers (continued):
Sharing a sentence is not in itself a finding about the gene and the disease.
anemia (continued). "In addition to promoting erythropoiesis, EPO may regulate hepcidin levels and thus influence the development of iron deficiency and/or anaemia." (PMID 39991164, 2025). "Given that erythropoietin has been shown to confer neuroprotection in hypoxic-ischemic conditions, future research should examine whether the combined effects of iron deficiency and antibiotic exposure differ based on anemia status." (PMID 40863165, 2025). "Recombinant human erythropoietin (rhEPO) is a form of therapy that is often resorted to because of its ability to reverse renal anemia, even though, in order to maintain desired laboratory parameters associated with anemia, dosing is individual and varies in each patient." (PMID 40725745, 2025). "In diabetic patients with kidney disease, anemia may arise due to a deficiency in erythropoietin, a hormone responsible for red blood cell production, or a decreased responsiveness to this hormone, known as erythropoietin resistance." (PMID 39099900, 2024). "While recombinant human EPO has been a standard treatment for CKD-related anemia for over two decades, some studies have indicated that targeting higher hemoglobin concentrations with EPO treatment or higher ESA doses may elevate the risk of stroke, hypertension, thrombosis, and mortality." (PMID 38311719, 2024). "Stunting affects the production of red blood cells and hemoglobin through mechanisms such as decreased erythropoietin production due to the action of proinflammatory cytokines, and deficiency in the intake of essential nutrients such as iron, vitamins and minerals, exacerbating the onset of anemia." (PMID 38564615, 2024). "Additionally, anemia is a prevalent characteristic observed in the adult population during sepsis, resulting from iatrogenic blood loss, reduction in serum iron levels and erythropoietin synthesis, and a decrease in the lifespan of erythrocytes." (PMID 38793057, 2024). "External factors including P. falciparum malaria may induce a pro-inflammatory environment that promotes the activation of auto-reactive lymphocytes; this could result in the production of antibodies such as anti-EPO which may interfere with the biological functions of EPO and cause anaemia." (PMID 36989322, 2023). "Moreover, AKI associated with hyperchloremia might affect erythropoietin levels, resulting in anemia." (PMID 37520482, 2023). "In addition to erythropoietin deficiency, hypo-responsiveness to erythropoietin may occur due to increased glycation of erythropoietin receptors can potentiate the development of anemia in type-2 diabetic patients." (PMID 37163539, 2023). "CKD-induced anemia is based on multiple mechanisms such as folate (vitamin B12) and iron deficiency, GI tract bleeding, severe hyperparathyroidism, shortened red blood cell survival rate, systemic inflammation, and decreased erythropoietin synthesis in response to renal hypoxia." (PMID 36827665, 2023). "Several factors, such as reduced iron absorption, blood loss, chronic inflammation, hyperparathyroidism, drugs (e.g., ACE-I, ARB, aspirin) and erythropoietin deficiency/hyporesponsiveness to erythropoietin, might cause the development of ID/ ID anemia in patients with CKD." (PMID 36617559, 2023). "Finally, both CKD and HF are frequently accompanied by anemia, which is due to a constellation of diverse factors, including relative erythropoietin deficiency, uremia-induced inhibitors of erythropoiesis, short erythrocyte survival, and disturbed iron homeostasis." (PMID 37763045, 2023). "In addition, in patients with anemia, the use of high-dose erythropoietin may increase the risk of cerebrovascular disease by increasing hypertension, vascular sclerosis, and blood viscosity." (PMID 37884871, 2023). "Moreover, the present iron deficiency (either true or functional) with anemia or EPO administration, contributes to high iFGF23 levels, that influence phosphate, PTH, and vitamin D metabolism defined as chronic kidney disease-mineral and bone disorder (CKD-MBD)." (PMID 36831276, 2023).
anemia (continued). "However, the financial burden of EPO therapy must be weighed against the expenses of blood transfusions as well as the health and economic consequences of complications associated with postoperative anemia." (PMID 38041115, 2023). "Anemia is a common complication of hypothyroidism and may be associated with bone marrow stimulation suppression, decreased erythropoietin production, nutritional deficiencies, and coexisting disorders, suggesting a complex mechanism for the development of postoperative anemia due to hypothyroidism." (PMID 37537620, 2023). "Constant macrophage infiltrate into adipose tissue and the local pro-inflammatory cytokines change in obesity may lead to impaired erythropoietin production and altered response of erythroid precursors, which has been a recognized mechanism of anemia associated with chronic diseases." (PMID 38150411, 2023). "The positive correlation between CD4 counts with RBC, Hgb and HCT among MHC could be explained most likely by the fact that decreased CD4 count as HIV disease progresses could cause anemia by myelosuppression from HIV that impairs erythropoietin, malaria may also induce removal of parasitized RBC." (PMID 35245289, 2022). "The major causes of severe anemia in PbANKA-infected mice include destruction of infected erythrocytes caused by the multiplication of parasites or by the activity of reticuloendothelial cells in the spleen, increased erythrocyte fragility, suppression of erythropoietin, and dyserythropoiesis." (PMID 35479191, 2022). "Anaemia in critically ill surgical patients may result from a wide range of etiologies, consisting of blood loss, persistent/dysregulated inflammation, deficiency of erythropoietin, impaired erythropoietic response, and nutritional deficiencies." (PMID 36128261, 2022). "Anemia can be caused by both chronic kidney and liver diseases with the feature of decreased hemoglobin and circulating erythrocytes, which is related to inadequate production of erythropoietin in the kidney, accumulation of inflammation, and deficiency of iron." (PMID 35620283, 2022). "Treatment for anemia may involve discontinuing medication with renal side effects or taking erythropoietin, folate, vitamin B12, or iron because the causes of anemia in patients with HF include impaired renal perfusion, nutritional deficiency, chronic inflammation, and certain medications." (PMID 35581275, 2022). "Jelkmann (2011) stated that multiple mechanisms might contribute to anemia in renal diseases; tubular atrophy during chronic kidney disease generates tubule-interstitial fibrosis, leading to a reduction of erythropoietin synthetic capacity contributes to the associated anemia." (PMID 35576029, 2022). "Additionally, regeneration of renal erythropoietin secreting cells can be a major cause of restoration of renal erythropoietin hormone to a normal level, stimulating erythropoiesis, which ultimately improves anemia." (PMID 36065849, 2022). "Therefore, the renal anemia in DN is associated with renal deterioration with a possible causal effect and the treatment of DN related anemia with EPO may slow the deterioration of DN." (PMID 35453626, 2022). "Erythropoietin (EPO) may be a mediator of CEC expansion caused by anemia in sepsis." (PMID 35251018, 2022). "However, reduced EPO level is considered the main factor that causes anemia of CKD." (PMID 35628849, 2022). "In the absence of intestinally derived FGF15, VSG leads to an even greater increase in hydrophobic bile acids which we speculate leads to anemia of chronic disease and increased EPO and FGF23 levels that likely contribute to great loss of bone mass, BMAT, muscle mass, and cardiac hypertrophy." (PMID 34362888, 2021). "Therefore, deficiency of EPO is the major cause of anemia in chronic kidney disease." (PMID 34113638, 2021). "Similarly, erythropoietin-(EPO)-producing iPSC)-derived nephrons could improve anemia associated with terminal kidney failure." (PMID 34722569, 2021).
anemia (continued). "However, the economic cost of EPO therapy must be balanced against the costs of blood transfusion and against the health and economic consequences of complications associated with postoperative anaemia." (PMID 34838063, 2021). "Additionally, the effects of carnitine supplementation on erythropoietin-resistant anemia may be associated with differences in the carnitine supplementation dose, supplementation period, and patient background." (PMID 34805230, 2021). "Vitamin-C deficiency may become especially important in patients with iron overload syndrome, which is common in the settling of transfusions for anemia as well as from chronic hemolysis and high red cell turnover driven by elevated erythropoietin concentrations, which are typical of PK deficiency." (PMID 34744776, 2021). "For instance, mutated mice with systemic EPO-deficiency have reduced exercise performance, associated with oxidative and metabolic stress in skeletal muscle and reduced expression of fast oxidative muscle fibres; yet, these observations were done in the presence of severe anaemia." (PMID 34142210, 2021). "Because of the association of anemia with high serum EPO in extremely premature infants and because of the known increase in serum Epo in the hWtEPOR mice, we measured hematocrits in WT and hWtEPOR mice raised in RA or the OIR model to assess whether hWtEPOR mice experienced anemia." (PMID 32785675, 2020). "Finally, we identified that a higher baseline anti-EPO antibody level was an independent risk factor for higher EPO demand, which may provide a novel strategy for prevention or risk classification of anemia as well as the direction of ESA use." (PMID 32318578, 2020). "Thus, EPO therapy can improve anemia in CKD and decrease cardiovascular disease risk." (PMID 31217925, 2019). "Moreover, other factors are suggested for the earlier onset of anemia in diabetic patient including severe symptomatic neuropathy leading to efferent sympathetic denervation of the kidney along with loss of appropriate erythropoietin; systemic inflammation; and inhibition of erythropoietin release." (PMID 31805098, 2019). "Iron deficiency anemia associated with inflammatory disorders, including kidney injury is attributed to rapid decline in renal function associated with rapid retention of nitrogenous waste products and decreased production of EPO, the main hormone of erythropoiesis." (PMID 30936264, 2019). "In addition to EPO, iron deficiency may contribute to development of anemia in inflammatory kidney disease." (PMID 30936264, 2019). "Therefore, the erythropoietin stimulating agents are administrated in CKD-associated anemia." (PMID 31217925, 2019). "Anemia is a common clinical condition in malignancy, which may result from blood loss, impaired erythropoiesis due to inadequate production or efficacy of erythropoietin, decreased availability of iron or from decreased life span of circulating erythrocytes." (PMID 26872376, 2016). "However, it remains unclear whether the main cause of anemia is a loss of EPO production capacity or a derangement in oxygen sensing." (PMID 26430892, 2015). "Other conditions causing anemia are inherited hematologic diseases such as sickle cell anemia or thalassemia causing hemolytic anemia, cancer treatments (chemotherapy and radiation), and indirect causes, such as lower erythropoietin (EPO) production due to kidney disease." (PMID 25690552, 2015). "In addition, this anemia and the associated kidney hypoxia favour the development of fibrosis, angiogenesis and inflammation that may underlie a resistance to EPO stimuli and reduced iron availability." (PMID 25867633, 2015). "Considering that both hemoglobin and erythropoietin are affected, the findings of studies aimed at determining gender associations with anemia among full term infants particularly in the early months can be used to discuss the observations of this study since they may reflect the iron stores." (PMID 24007344, 2013).
anemia (continued). "The most well-known cause is inadequate production of erythropoietin, but there are also other causes leading to impaired erythropoiesis (reduced proliferative activity of erythroid precursors in bone marrow, reduced survival of red cells, and decreased iron availability), contributing to anemia." (PMID 23555091, 2013). "As a result anti-EPO antibodies may be implicated in malaria anaemia cases." (PMID 23978045, 2013). "For symptomatic and persistent anaemia associated with imatinib, EPO may therefore be considered." (PMID 22950685, 2012). "A possible explanation to the differences between the two studies could be that the high prevalence (36%) of severe anemia among SM cases in the present study is diluting the effect of other factors linked to the clinical condition in modulating the relation between EPO and Hb." (PMID 21912616, 2011). "Deficient production of hepcidin causes systemic iron overload in iron-loading anemias such as beta-thalassemia; whereas hepcidin excess contributes to the development of anemia in inflammatory disorders and chronic kidney disease, and may cause erythropoietin resistance." (PMID 20066043, 2010). "Anemia of CKD may reflect dysregulated erythropoietin release as well as loss of peritubular cells." (PMID 17910755, 2007). "However, the suggested mechanisms include a direct effect of the virus itself, bone marrow suppression as a result of cytokine release, anaemia as a result of chronic inflammation or opportunistic infection, reduced erythropoietin production and response, and deficiency of vitamin B12 or folates." (PMID 18330066, 2007). "Hence, correction of tumour-associated anaemia – for example, with recombinant erythropoietin – may improve the pO2 in tumour tissue." (PMID 14647149, 2003). "Laboratory tests revealed a profound anemia resistant to erythropoietin, severe hypoparathyroidism, and diffuse osteolytic lesions in the spine and pelvis." (PMID 41924686, 2026). "In a 2019 interview with Dillashaw, former UFC fighter Chael Sonnen reported that he was prescribed EPO (‘Procrit’) by a physician for anaemia during a training camp." (PMID 39692599, 2026). "In some anemias EPO is markedly elevated relative to the degree of anemia, whereas in others it is inappropriately low." (PMID 41875175, 2026). "Anaemia is a common symptom in patients with CKD, caused by insufficient erythropoietin (EPO) production, abnormal iron metabolism, blood loss, inflammation, nutrient deficiencies and oxidative stress." (PMID 41457350, 2026). "Anemias present puzzling imbalance between hemoglobin (Hb) and the main regulator of red blood cells - the hormone erythropoietin (EPO)." (PMID 41875175, 2026). "At the same time, erythropoietin (EPO) was used to treat anemia, and nifedipine tablets were used to control blood pressure." (PMID 41517692, 2026). "In chronic kidney disease (CKD), reduced renal synthesis of active vitamin D and impaired endogenous EPO production frequently coexist, contributing not only to disturbances in mineral metabolism and anaemia, but possibly also to immune dysregulation." (PMID 42111895, 2026). "Following a diagnosis of VEXAS syndrome, he was treated with corticosteroids and methotrexate but developed refractory anemia and required erythropoietin therapy." (PMID 42136818, 2026). "Background and Objectives: Anemia is a frequent complication of chronic kidney disease (CKD), primarily attributed to erythropoietin deficiency." (PMID 42195073, 2026). "Elevated erythropoietin (EPO) concentration associates with thrombotic risk in hypoxic conditions, hereditary erythrocytosis and treatment of anaemia with recombinant EPO." (PMID 42052798, 2026). "Anemia and dysregulation of the erythropoietin (EPO) axis further contribute to metabolic decompensation." (PMID 41602347, 2026).
anemia (continued). "Desidustat had a greater improvement in quality of life score (Chronic Kidney Disease-Anemia Questionnaire (CKD-AQ) compared to erythropoietin at each time interval, reflecting lower symptom burden." (PMID 41859634, 2026). "Anemia worsening during ruxolitinib was reported in 58% of cases, and 64% were treated with concomitant subcutaneous erythropoietin." (PMID 40955124, 2026). "Anemia in children with CKD is often due to reduced erythropoietin production from renal damage, with additional contributions from factors like iron deficiency, inadequate diet, poor iron absorption, and blood loss through tests or dialysis." (PMID 41073614, 2026). "Fourteen patients (36%) received fedratinib, mainly as second‐line therapy, with a median exposure of 10.5 months (range, 2–22 months), and anemia worsening and concomitant use of erythropoietin were reported in 31% and 33% of cases, respectively." (PMID 40955124, 2026). "BACKGROUND: Recombinant human erythropoietin (epoetin) is the mainstay of anemia management in hemodialysis patients." (PMID 41781903, 2026). "Recombinant EPO and its derivatives have been widely used for decades as erythropoiesis‐stimulating agents (ESAs) to treat anemia, particularly in patients with chronic kidney disease (CKD)." (PMID 41556618, 2026). "One patient who developed grade 3–4 anemia and neutropenia was managed with erythropoietin and G‐CSF, respectively." (PMID 41510882, 2026). "On April 24, 2021, the Hb levels were rechecked at 100 g/L, and EPO was switched to Roxadustat capsules to improve anemia." (PMID 41517692, 2026). "Modeling of DD‐CKD patients' anemia with reduced RBC lifespans predicts increased endogenous EPO within the normal and slightly above‐normal range can achieve hemoglobin concentrations between 10 and 12 g/dL." (PMID 41376433, 2026). "The development of potent and efficacious Abs as ESAs marks a transformative advance in the treatment of anemia, particularly in patients with low endogenous EPO such as those with CKD and related conditions." (PMID 41556618, 2026). "Erythropoietin-stimulating agents can be used if fatigue is due to chemotherapy-induced anaemia (though concerns about safety limit this to certain patients)." (PMID 40498265, 2025). "The synthetic form of erythropoietin is used to treat anaemia that results from chronic kidney disease." (PMID 40116328, 2025). "There have been case reports where Jehovah’s Witnesses with severe anemia were managed successfully with alternative management strategies such as erythropoietin injections or advanced treatment such as anti-angiogenic medications." (PMID 41523403, 2025). "Understanding EPO responsiveness and its interaction with erythrocyte homeostasis is therefore critical for optimizing anemia management in HD patients." (PMID 41383483, 2025). "A well-known phenomenon is that anemia's high compensatory erythropoietin levels also induce reactive thrombocytosis." (PMID 40171171, 2025). "We examined the correlation between serum vitamin B6 concentration and various indicators of anemia, including Hb indices, iron profile, and erythropoietin dose." (PMID 39871236, 2025). "In conditions such as chronic kidney disease or end-stage renal disease, erythropoietin levels are often insufficient to meet erythropoietic demands, exacerbating anemia." (PMID 39881295, 2025). "Showed that 25(OH)D has an important positive regulation effect on renal anaemia, and active vitamin D treatment can increase EPO levels in the body and improve anaemia." (PMID 40837352, 2025). "EPO, a cornerstone of anemia management in ESRD, exerts cytoprotective effects on mature erythrocytes by attenuating calcium influx, ROS generation, and caspase activation—ultimately reducing eryptosis." (PMID 41383483, 2025). "Even though serum EPO levels tend to increase as age advances in healthy individuals, an intriguing observation is that anemic older adults exhibit lower EPO levels compared to their younger counterparts facing anemia." (PMID 40777989, 2025).